STAT3 (signal transducer and activator of transcription 3)
Diseases named in the same sentence as STAT3 in open-access papers (continued):
Sharing a sentence is not in itself a finding about the gene and the disease.
gastric adenoma (6 papers, 2010 to 2022). A neoplastic polyp that arises from the stomach. "Thus, the development of gastric adenomas in gp130F/F mice and the associated development of TLSs are tightly coupled, and are dependent on hyperactivation of STAT3 via gp130 signalling." (PMID 29417587, 2018). "In order to dissect the mechanisms by which miR-21 suppression limited the growth of Stat3-dependent gastric adenomas, we examined the expression of several candidate bona fide tumor suppressor genes that are regulated by Stat3 and miR-21." (PMID 35053428, 2022). "Here, we exploit the Gp130F/F mouse as a pre-clinical model of Stat3-dependent gastric adenoma formation to delineate the contribution of miR-21 expression to early disease initiation and its underlying molecular mechanism." (PMID 35053428, 2022). "In Gp130F/F mice, a disruption of the Socs3-dependent negative feedback loop on the shared IL-6 cytokine family gp130 receptor subunit results in excessive STAT3 signaling that promotes the spontaneous development of gastric adenomas from 6 weeks of age." (PMID 36552868, 2022). "Collectively, our results support the existence of a therapeutically targetable STAT3/miR-21 signaling cascade that partakes in gastric adenoma formation in mice through the impairment of the expression of tumor suppressors in favor of the genes involved in EMT and extracellular matrix production." (PMID 35053428, 2022). "In this model, gastric adenomas spontaneously and reproducibly develop with 100% penetrance in 4‐week‐old mice with an absolute genetic dependence on bi‐allelic expression of the il11rα and Stat3 genes, but completely independent of IL6 signaling." (PMID 30885958, 2019).
glomerular disease (6 papers, 2013 to 2025). "Among the up-regulated proteins, there were several known glomerular disease associated proteins, such as the transcription factors signal transducer and activator of transcription 3, complement compoents." (PMID 36503536, 2022). "Expression arrays from kidney biopsies with various types of glomerular diseases, deposited in Nephroseq, were interrogated for glomerular expression of genes downstream of STAT3 signaling." (PMID 40880189, 2025). "Similarly, pharmacological blockade and genetical knockdown of STAT3 reduced macrophage infiltration in diabetic mice and prevented glomerulopathy." (PMID 31846485, 2019). "However, Sgpl1 KO mice treated in the neonatal period with AAV-SPL 2.0 showed minimal glomerular disease and almost no STAT3 pathway activation." (PMID 37958544, 2023).
HIV-1 infection (6 papers, 2001 to 2025). The type species of lentivirus and the etiologic agent of acquired immunodeficiency syndrome (AIDS). "STAT3 is a central regulator of both Th17 and Treg differentiation, and its dysregulation in HIV-1 infection plays a key role in the imbalance of these subsets." (PMID 41009690, 2025). "STAT3 plays a central role in cytokine signaling pathways (particularly IL-6 and IL-10), and type I IFNs, which are dysregulated in HIV-1 infection." (PMID 41009690, 2025). "As we described and observed before and herein, cmMTB-treated cells were positive for the M(IL-10) markers (CD16+CD163+MerTK+ and phosphorylated STAT3), and displayed a high rate of HIV-1 infection, as compared to those treated with cmCTR." (PMID 32223897, 2020). "Consistent with their ability to activate STAT3, IL-6 and IL-10 also induced miR-29 and suppressed HIV-1 infection in HLACs." (PMID 26108174, 2015). "Collectively, these findings demonstrate a novel and rapid miR-29-mediated antiviral activity of IL-21 that acts through STAT3 in target CD4 T cells to limit initial HIV-1 infection." (PMID 26108174, 2015). "However, future work in experimental animal models that allow genetic ablation or depletion of IL-21/STAT3 before HIV-1 infection will be required to more precisely define the in vivo activity of IL-21 at early stages of lentiviral infections." (PMID 26108174, 2015). "Regulation of the GLS1 promoter by IFN-α or HIV-1 infection is specific to STAT1 because when we used STAT3 antibody in the ChIP assay we found that neither IFN-α nor HIV-1 infection significantly increased binding between STAT3 and the GLS1 promoter (data not shown)." (PMID 22479354, 2012).
immune thrombocytopenia (6 papers, 2022 to 2025). "More than half of the patients with STAT3 GOF mutations present with autoimmune cytopenia (immune thrombocytopenic purpura (ITP), 24/42 described patients), autoimmune hemolytic anemia (AIHA, 19/28), and neutropenia (9/28)." (PMID 37140667, 2023). "The decrease in protein levels of STAT3 ultimately inhibits Th17 cell differentiation and inhibits the development of immune thrombocytopenia (ITP) in vivo." (PMID 38172648, 2024).
inflammatory breast carcinoma (6 papers, 2015 to 2025). An advanced, invasive breast adenocarcinoma characterized by the presence of distinct changes in the overlying skin. "This study provides novel mechanistic insights into the capacity of the inflammatory cytokine IL-6 and its associated STAT3-dependent signaling pathway to stimulate proliferation in trans between individual sub-clones in a model of heterogeneity in inflammatory breast cancer." (PMID 35565421, 2022). "Intriguingly, a recent study of inflammatory breast cancer demonstrated a JAK2/STAT3 signaling axis that conferred chemoresistance and EMT, consistent with our findings of CAF2-regulated malignant cell traits." (PMID 38388711, 2024). "Immune‐suppressing M2‐like macrophages in inflammatory breast cancer (IBC) have been found to secrete high levels of IL‐8 and growth‐regulated oncogene (GRO) chemokines which activate the STAT3 pathway, and are the main driving force for the formation of the CSCs." (PMID 34914196, 2022).
insomnia (6 papers, 2021 to 2026). A sleep disorder characterized by difficulty in falling asleep and/or remaining asleep. "Further, the components in CXEO-FCEO were shown by network pharmacological analysis to act broadly on insomnia-associated STAT3, 1L-1β targets, which may act together on the JAK-STAT pathway." (PMID 39334868, 2024).
leiomyosarcoma (6 papers, 2005 to 2017). An uncommon, aggressive malignant smooth muscle neoplasm, usually occurring in post-menopausal women. "Murine leiomyosarcoma cell lines also exhibited constitutive activation of phosphorylated STAT3 (pSTAT3)." (PMID 26555296, 2015). "Furthermore, recent observations by Zhang and coworkers point to an important function for STAT3 in both tumorigenesis and metastasis formation in leiomyosarcoma, due to signaling by hepatocyte growth factor/scatter factor." (PMID 15647107, 2005). "The lack of phosphorylation in this case suggests that the leiomyosarcoma may not depend on the STAT3 pathway." (PMID 25861239, 2015).
Lewis lung carcinoma (6 papers, 2015 to 2023). "Interestingly, Lewis lung carcinoma cells secrete extracellular vesicles containing interleukin-6 that induced lipolysis in 3T3-L1 cells via the STAT3 pathway." (PMID 37316878, 2023).
liposarcoma (6 papers, 2019 to 2023). A usually painless malignant tumor that arises from adipose tissue. "In the liposarcoma cell model, 6-shogaol induces apoptosis by inhibiting STAT3 phosphorylation in SW872 liposarcoma cells, leading to caspase-3 activation and PARP cleavage." (PMID 37875983, 2023). "Western blotting verified that Apatinib downregulated the TYMS/STAT3/PD-L1 pathway and inhibited liposarcoma proliferation by suppressing the RRM2/PI3K/AKT/mTOR pathway." (PMID 34868934, 2021). "While the previous study revealed TYMS downregulation inhibited STAT3 phosphorylation in liposarcoma cell and RRM2 downregulation inhibited the AKT signaling pathway." (PMID 34868934, 2021). "In this study, we have demonstrated that 6-Shogaol has anti-survival and pro-apoptotic effects on SW872 human liposarcoma cells, and these effects are mediated through regulation of the intrinsic caspase pathway, oxidative stress, STAT-3, AMPK, and ER stress." (PMID 32998376, 2020). "In summary, this is the first study reporting that AZD1208 has a cytostatic effect in human liposarcoma cells, which is be mediated through control of the expression and/or phosphorylation of Pim kinases, 4EBP-1, mTOR, S6, eIF-2α, STAT-3 and AMPK." (PMID 30654529, 2019). "In this study, we report for the first time that AZD1208 inhibits the growth of 93T449 human liposarcoma cells through Pim-3, 4EBP-1, mTOR, S6, eIF-2α, STAT-3 and AMPK." (PMID 30654529, 2019). "In summary, this is the first report demonstrating that AZD1208 inhibits growth of liposarcoma cells and that this activity is mediated through Pim-3 kinase, STAT-3, mTOR, S6 and AMPK expression and phosphorylation pathways." (PMID 30654529, 2019). "Therefore, we assessed PD-L1 expression and changes in the STAT3 pathway in liposarcoma cell lines treated with Apatinib." (PMID 34868934, 2021). "In summary, this is the first study reporting that 6-Shogaol has strong anti-survival and proapoptotic effects on SW872 human liposarcoma cells, and these effects are mediated through regulation of the intrinsic caspase pathway, oxidative stress, STAT-3, AMPK, and ER stress." (PMID 32998376, 2020). "Therefore, Apatinib might inhibit STAT3 and then downregulate PD-L1 expression in liposarcoma cells." (PMID 34868934, 2021). "However, until now, 6-Shogaol regulation of STAT-3 expression and phosphorylation levels in human liposarcoma cells is unknown." (PMID 32998376, 2020). "Here we report that tetrandrine at 10 μM has strong anti-proliferative, anti-survival, and pro-apoptotic effects on SW872 human malignant undifferentiated liposarcoma cells by controlling the intrinsic caspase pathway, XIAP, STAT-3, and ER stress." (PMID 35740967, 2022). "Until now, little is known about the phosphorylation of STAT-3 and AZD1208 regulation of the STAT-3 phosphorylation in human liposarcoma cells." (PMID 30654529, 2019). "Apatinib may inhibit liposarcoma cell proliferation through RRM2/PI3K/AKT/mTOR signaling pathway, and down-regulate PD-L1 through TYMS/STAT3 signaling pathway." (PMID 34868934, 2021). "Apatinib might inhibit liposarcoma cell proliferation through the RRM2/PI3K/AKT/mTOR signaling pathway and downregulate PD-L1 via the TYMS/STAT3 signaling pathway." (PMID 34868934, 2021).
meningioma (6 papers, 2013 to 2024). A generally slow growing tumor attached to the dura mater. "Previously we have found that cerebrospinal fluid stimulation of leptomeningeal and meningioma cell proliferation is associated, in part, with activation of STAT3." (PMID 24188277, 2013). "Previously we have found that STAT3 phosphorylation/activation was associated with cerebrospinal fluid stimulation of irradiated leptomeningeal cell and meningioma cell proliferation." (PMID 24188277, 2013). "In the leptomeninges and one meningioma, cucrbitacin I’s effects correlated with reduced phosphorylation of STAT3." (PMID 24188277, 2013). "The effects of cucurbitacin I on cerebrospinal fluid stimulation of meningioma cell DNA synthesis phosphorylation/activation of JAK1, STAT3, pMEK1/2, p44/42MAPK, Akt, mTOR, Rb and caspase 3 activation were analyzed in human leptomeningeal and meningioma cells." (PMID 24188277, 2013). "In the grade II meningiomas, cerebrospinal fluid stimulated STAT3 phosphorylation in all and reduced phosphorylation of MEK1/2 in all and p44/42MAPK in one." (PMID 24188277, 2013). "In search of a STAT3 inhibitor, we tested cucrbitacin I on STAT3 activation in one leptomeningeal and meningioma culture." (PMID 24188277, 2013). "Upregulation of ERK1/2 T202/Y204 and downregulation of STAT3 mediated by AKAP12 may be resulting in the overexpression of CCND1 in high-grade meningiomas." (PMID 29391485, 2018). "Previously, we have found STAT3 to be activated in meningiomas, particularly higher grade tumors." (PMID 24188277, 2013). "In one grade II meningioma, co-administration of cerebrospinal fluid and cucurbitacin I appeared to increase STAT3 phosphorylation (M4) but this was in a case showing particularly robust proliferation in response to cerebrospinal fluid which might be harder to block." (PMID 24188277, 2013). "Many of these mechanisms are also involved in meningioma development and progression, such as the cell cycle, PI3K-AKT pathway, and STAT3 pathway." (PMID 38398158, 2024). "Fibroblast growth factor receptor-3 was found to induce the proliferation of meningioma cells via activation of the phosphoinositide 3 kinase-Akt-PRAS40-mTOR and STAT3 pathways." (PMID 27895530, 2016). "Importantly, FGFR2 and FGFR3 were detected in meningiomas, and FGF1 was shown to be able to stimulate meningioma cell proliferation by activation of AKT1 and STAT3." (PMID 35996584, 2022). "Moreover, cerebrospinal fluid activation/phosphorylation of STAT3, at least in human leptomeningeal and meningioma cells, appears to be independent of an IL-6 receptor-JAK-STAT3 pathway." (PMID 24188277, 2013). "Thus STAT3 activation may be via several cytokine/growth factor receptor/kinases and/or by the MEK-1-MAPK and PI3k-Akt-mTOR pathways that we and others have found to be mitogenic to meningioma cells." (PMID 24188277, 2013).
myeloid malignancies (6 papers, 2013 to 2023). "To explore whether DNA hypermethylation associated with STAT3 activation could be therapeutically targeted, we evaluated the effects of azacitidine, a hypomethylating agent widely used to treat myeloid malignancies." (PMID 34075200, 2021). "Mechanistically, we demonstrate that STAT3 controls NF-κB-induced IL-8 expression by sequestering NF-κB within the cytoplasm, thereby inhibiting IL-8-mediated myeloid tumour infiltration and tumour vascularization and hence tumour progression." (PMID 25734337, 2015). "STAT3 transcription factors could lend to malignant cells the ability to escape apoptosis induced by a variety of external stimuli, including chemotherapeutic drugs, such as doxorubicin, and have been described to be important in the pathogenesis of myeloid malignancies." (PMID 24283803, 2013).
peripartum cardiomyopathy (6 papers, 2014 to 2023). Peripartum cardiomyopathy (PPCM) is an idiopathic, potentially fatal form of dilated cardiomyopathy that develops during the final month of pregnancy or within five months after delivery. "Endothelial cell STAT3 plays a key role in inflammation that underlies cardiovascular disease and contributes to adverse cardiomyocyte genetic reprograming during peripartum cardiomyopathy." (PMID 31069236, 2019). "STAT3 in endothelial cells contributes to adverse cardiomyocyte genetic reprograming, for instance, during peripartum cardiomyopathy." (PMID 31069236, 2019). "STAT3 conditional knockout mice developed peripartum cardiomyopathy in a dose-dependent manner (conditional knockout heterozygotes)." (PMID 25007941, 2014). "The role of STAT3 in peripartum cardiomyopathy was discovered in 2007." (PMID 25007941, 2014). "Women with peripartum cardiomyopathy have reduced levels of signal transducer and activator of transcription 3 (STAT3), increased cathepsin D, and decreased expression of manganese superoxide dismutase; the combination of which causes apoptosis, impaired angiogenesis, and oxidative stress." (PMID 24523698, 2014). "Blocking miR-146a with a specific antagomir causes the attenuation of peripartum cardiomyopathy clinical features in STAT3 conditional knockout mice, without affecting full-length prolactin-dependent milk production functions." (PMID 25007941, 2014).
Psoriasiform dermatitis (6 papers, 2016 to 2025). A skin abnormality characterized by redness and irritation, with thick, red skin that displays flaky, silver-white patches (scales). "Pharmacological restoration of the axis also has a proof-of-concept: a stable form of galectin-9 (a TIM3 ligand) suppresses contact hypersensitivity and IL-23–driven psoriasiform dermatitis, reducing IL-17/IL-22 and epidermal STAT3 activation." (PMID 41307843, 2025). "Taken together, these findings indicate that S1PR inhibition alleviates IMQ-induced psoriasiform dermatitis, coinciding with reduced STAT3 activation." (PMID 39833165, 2025). "In this study, we established a mouse model of psoriasiform dermatitis by intradermal IL-17A injection in STAT3 overexpressing mice." (PMID 37465147, 2023). "To elucidate whether the improved psoriasiform dermatitis observed in S1pr3-KO mice was due to a reduction in STAT3 in keratinocytes, we then investigated the mechanistic link between S1PR3 and STAT3 signaling in HaCaT keratinocytes." (PMID 39833165, 2025). "Finally, P90 NbnKrox20-Cre epidermises exhibit increased phosphorylation/activation of Stat3 (p-Stat3), p38 (p-p38), p44 (p-p44) and S6 ribosomal protein (p-S6) which are also hallmarks of psoriasiform dermatitis." (PMID 27050272, 2016).
renal failure (6 papers, 2015 to 2025). "Key inflammatory pathways, such as PI3K/AKT, JAK/STAT3, TLR/NF-κB, TNF-α, TGF-β1, can exacerbate structural damage in the kidneys of DN patients, ultimately contributing to renal insufficiency." (PMID 40181946, 2025).
Sezary syndrome (6 papers, 2012 to 2023). Sezary syndrome (SS) is an aggressive form of cutaneous T-cell lymphoma characterized by a triad of erythroderma, lymphadenopathy and circulating atypical lymphocytes (Sezary cells). "IL-21 leads to more specific activation of STAT3 in Sezary Syndrome, which in turn directly upregulates IL-21 expression leading to an enhanced IL-21 autocrine signaling loop." (PMID 36505769, 2022). "It has also been shown that the transcription factor, signal tranducer and activator of transcription 3 (STAT3), could also induce miR-21 expression in memory T cells obtained from patients with Sezary syndrome." (PMID 23272133, 2012). "MiR-21, an oncogenic miRNA found in most cancers, plays a major role in Sézary disease, where its expression in cancerous CD4 memory T cells is elevated relative to CD4 T cells in healthy patients, and its activity is associated with signal transducer and activator of transcription 3 (STAT3)." (PMID 36613640, 2022). "ChIP assay result validated that the constitutively activated signal transducer and activator of transcription 3 (STAT3) directly targets and activates pri-miR-21 in Sézary Syndrome (SS), a cutaneous T-cell lymphoma (CTCL)." (PMID 31139230, 2019).
soft tissue sarcoma (6 papers, 2007 to 2022). A malignant neoplasm arising from muscle tissue, adipose tissue, blood vessels, fibrous tissue, or other supportive tissues excluding the bones. "Among the STAT family, STAT-3 has been extensively studied due to its constitutive expression in many human cancers including soft tissue sarcoma cells." (PMID 30654529, 2019). "It binds with SH2-domain of STAT3 and effectively inhibits STAT3 dimerization and demonstrated inhibition of growth and survival of breast and soft tissue sarcoma cell lines." (PMID 24308725, 2013).
staphylococcus aureus infection (6 papers, 2013 to 2025). An infectious process in which the bacteria Staphylococcus aureus is present. "Staphylococcus aureus infection is one of the noteworthy characteristics of STAT3-deficient patients." (PMID 32944025, 2020). "The KEGG pathways associated with AD were mainly involved in the IL-10 signaling pathway, IL-4 and IL-13 signaling, TGF-beta receptor signaling, the TCR pathway during Staphylococcus aureus infection signaling, and the STAT3 pathways." (PMID 41471858, 2025). "Managing drug resistant Staphylococcus aureus infections, such as MRSA, is critical in patients with STAT3-HIES." (PMID 40491905, 2025). "Thus, it is intriguing to speculate that antimicrobial peptides that exhibit anti-staphylococcal activity and are regulated via STAT3 such as RNase 7 may be dysregulated in keratinocytes of HIES patients which may contribute to frequent Staphylococcus aureus infections." (PMID 23555696, 2013).